CD4 (CD4 molecule)
Diseases named in the same sentence as CD4 in open-access papers (continued):
Sharing a sentence is not in itself a finding about the gene and the disease.
latent infection (continued). "Total latent infection (no L8) was significantly increased in non-proliferating CD4+ T-cells co-cultured with all mDC subpopulations, CD14+ monocytes and B-cells, when compared to CD4+ T-cells cultured alone (p = 0.03)." (PMID 26362311, 2015). "Based on these results, we concluded that in resting CD4 T cells, only the HIV envelope-mediated entry but not the VSV-G-mediated endocytosis can lead to viral DNA synthesis and nuclear migration, which are a prerequisite for the establishment of HIV latent infection of resting CD4 T cells." (PMID 19851458, 2009).
Stroke (207 papers, 2010 to 2026). Sudden impairment of blood flow to a part of the brain due to occlusion or rupture of an artery to the brain. "Transgenic animals deficient in CD4+ or CD8+ T cells consistently have smaller infarcts in different stroke models." (PMID 40342517, 2025). "The present study explored the association of peripheral CD4+ Treg cells and prognosis in patients with acute ischemic stroke, and identified that higher circulating CD4+ Treg counts were associated with a better post-stroke prognosis." (PMID 40948641, 2025). "Our findings further substantiate that CD39 presence in CD39+ CD8+ T cells and CD39+ activated CD4 Tregs is inversely associated with stroke occurrence." (PMID 38323746, 2024). "Lower T cell percentage, CD3+, and CD4+ T‐cell counts 1–3 days after stroke were independently associated with increased risk of poor prognosis." (PMID 39205499, 2024). "When looking at lesion volumes in animal models of stroke, combined T and B cell deficiency, as well as selective depletion of CD4 or CD8 T cells, reduce lesion volumes." (PMID 36446955, 2022). "CD4 T cell infiltration has been implicated in stroke-associated neuroinflammation and CD4 cell deficit has shown beneficial effects by reducing infarction." (PMID 35250546, 2022). "Rising counts of circulating CD4+CD28- cells were associated with an increased risk of stroke recurrence and death over the next year." (PMID 34711943, 2022). "In particular, considering pathogenic IS phenotypes, the percentage of CD4 + T-bet + T cells was significantly higher after 7 days from stroke onset than baseline both in ATHS and CES patients (p = 0.0332 and p = 0.0340, respectively)." (PMID 36180482, 2022). "This suggests that these variables were considered confounders when assessing risk factors of stroke, while other predictors such as CD4 count and age were the main risk factors in multivariate logistic regression models." (PMID 34983408, 2022). "The CD69+CD4+ T cell phenotype inversely correlated with stroke severity and was associated with naive and central memory T (TCM) cells." (PMID 33205448, 2021). "Brain large artery atherosclerosis in PLWH is associated with lower CD4 nadir and higher CD4 count during the stroke event." (PMID 34239489, 2021). "Levels of IFN-γ and IP-10 are also reduced following CD4 T cell depletion 3 days after stroke onset, and this is associated with improved behavioral outcomes." (PMID 32477327, 2020). "In this study, we have shown some unprecedented results, suggesting that the protective effects of CD4 T cell deficits against stroke is linked with inhibited oxidative stress and enhanced cell signaling survival pathways." (PMID 32832192, 2018). "Nevertheless, the underlying protective mechanisms of CD4 deficits against stroke are poorly understood." (PMID 32832192, 2018). "Even small CD4+ cell count deficits are associated with increased risk of cardiovascular disease, stroke, and cancer in adult HIV patients." (PMID 29927784, 2018). "Taken together, we provide solid evidence that the protective effect of CD4 T cell deficits in stroke is linked with the inhibited pro-inflammatory and oxidative responses, and with the enhanced activities of the Akt/mTOR pathways." (PMID 32832192, 2018). "While the role of CD4 counts was equivocal for MI/CHD, CD4 counts < 200 cells was a risk factor for death (HR 2.98, 2.67–3.32), stroke (HR 1.91, 1.44–2.54) and ICH (HR 4.61, 2.09–10.2)." (PMID 28493892, 2017). "Higher CD4+ counts (a function of ART) were associated with reduced stroke risk, suggesting that HIV treatment is indeed beneficial overall." (PMID 26683649, 2016). "In contrast, those on longer-term treatment had a much higher CD4+ count, possibly explaining the reduced stroke risk in this group." (PMID 26683649, 2016). "FoxP3+CD4+ Tregs appear to exert an unfavorable role as immunosuppressive modulators and increase infection susceptibility following stroke." (PMID 23983771, 2013).
Stroke (continued). "It is imperative to advance our understanding and authenticate the roles of FoxP3+CD25+CD4+ Tregs and their underlying mechanisms in stroke pathophysiology." (PMID 23983771, 2013). "Secondly, the fundamental questions regarding FoxP3+CD25+CD4+ Tregs, such as their temporal and spatial dynamics, significance, and underlying immunomodulatory mechanisms in stroke, need to be answered." (PMID 23983771, 2013). "TD CD4+ %T cell and CM CD8br %CD8br are linked to an increased risk of stroke." (PMID 38894965, 2024). "CD4 + ‐mediated stroke damage is mainly caused by the pro‐inflammatory effect of Th1 cells." (PMID 37905592, 2023). "In addition to CDC42, the association of CD4+ T cells with mental health and cognitive function is also a key issue in stroke patients' management." (PMID 37703110, 2023). "CD4 + CD28null cells which have advanced effector functions have been found at an increased frequency in ischemic stroke patients which was also associated with stroke severity." (PMID 35858901, 2022). "Multivariate logistic regression indicated that age of 30–55 years (OR 1.903, 95% CI 1.005–3.603, p = 0.048), age of ≥ 55 years (OR 4.104, 95% CI 1.928–8.737, p < 0.001), and CD4 count of < 200 cells/μL (OR 2.005, 95% CI 1.008–3.985, p = 0.047) were associated with increased odds of stroke." (PMID 34983408, 2022). "Interestingly, this CD69+CD4+ T cell phenotype inversely correlated with stroke severity and was associated with naive and TCM cells." (PMID 33205448, 2021). "Our results showed that the alteration of different T cell phenotypes was involved in the stroke process and that PD-1 may be implicated in the mechanisms of CD4+ T cell differentiation in the stroke process." (PMID 30013463, 2018). "In addition, observational studies have shown that high plasma HIV viral load and/or low CD4+ T-cell counts increase the risk of stroke in HIV-infected individuals." (PMID 28617855, 2017). "Likewise, a low number of senescence‐like CD4 T cells also predicted decreased risk of death from MI and stroke specifically after adjusting for gender, CMV, disease count, and cytokines (HR 0.62 [0.40–0.95], P = 0.027)." (PMID 26696322, 2016). "We found that lower CD4+ count was a major risk factor for HIV-related stroke risk." (PMID 26683649, 2016). "Third, our stroke patients showed a significantly higher prevalence of a previous stroke compared to controls thus, this higher previous cerebrovascular morbidity, could be linked to the higher degree of CD4+CD28− peripheral percentage in stroke patients." (PMID 25997053, 2015). "Therefore, future investigations should focus on the reliable definition as well as the further determination of the real roles and underlying mechanisms of FoxP3+CD25+CD4+ Treg-mediated immune regulation following stroke." (PMID 23983771, 2013). "This study revealed an association between the high probability of death after a stroke or new ischemic episodes and the CD4+CD28 null lymphocyte cell count, and proposed that the number of these lymphocytes could serve as a warning biomarker against recurrence of an ischemic event or death." (PMID 33922467, 2021). "Flow cytometry analysis showed that compared with the MCAO + IgG group, the ratio of CD4+CD25+Foxp3+ Tregs increased significantly in the MCAO + IL‐2:IL‐2 Ab group on the 14th day after stroke." (PMID 41552852, 2026). "Interaction analysis revealed a significant gender-specific effect of CD4+ Treg cell counts on stroke prognosis (interaction p = 0.0198)." (PMID 40948641, 2025). "CD4+ helper T cells secrete IFN-γ and IL-21, and deficiency of these cytokines significantly attenuates cerebral infarct volume in experimental stroke models." (PMID 40659887, 2025). "Segmented regression analysis demonstrated that the effect of CD4+ Treg cells on the prognosis of stroke has significant heterogeneities over a number of thresholds." (PMID 40948641, 2025).
Stroke (continued). "In mice with stroke, CD4+ T cell accumulation was noticed for a 30-day period, with a peak on the 14th day of stroke." (PMID 40342517, 2025). "This correlation suggests that CD4 T-cells play a significant role in stroke pathology and recovery, making them a critical focus of interest." (PMID 40012683, 2025). "Gender plays a critical role in modulating the immunoregulatory effects of CD4+ Treg cells on stroke prognosis, with male patients deriving significant benefit from higher Treg cell counts." (PMID 40948641, 2025). "Regulatory T cells (Tregs), particularly the CD4 + subset, play a pivotal role in suppressing inflammation and promoting neurorepair after stroke." (PMID 40948641, 2025). "Studies have shown that CD4+ T cells act as immunomodulators after a stroke and display a protective effect when coping with inflammatory brain damage." (PMID 39958615, 2025). "Brain-infiltrating CD4+ T cells release Nox2-derived superoxide following stroke, which promotes neuronal death." (PMID 40352928, 2025). "The interaction analysis confirmed that gender significantly moderated the relationship between CD4+ Treg cell counts and stroke prognosis (p = 0.0198)." (PMID 40948641, 2025). "The reduction of CD4+ or CD8+ T cells within 24 h after stroke resulted in a decrease in infarct size." (PMID 41368357, 2025). "CD4 T-cells are recruited 24 h after a stroke, but peak infiltration occurs 3–4 days after the stroke." (PMID 40012683, 2025). "While there are a variety of CD4 T-cell subsets, the Th1 subset has shown promotion of stroke neuropathology." (PMID 40012683, 2025). "In AIS patients, the number of CD4+CD28- T cells in the blood is positively related to the National Institute of Health Stroke Scale (NIHSS) score." (PMID 40352928, 2025). "Elucidating this is crucial, as various stroke models have demonstrated the secondary neuropathological effect of stroke-induced CD4 T-cells." (PMID 40012683, 2025). "CD4+ regulatory T cells (Tregs), a subtype of T cells with immunosuppressive effects, have been shown to be important in stroke." (PMID 39878387, 2025). "This study highlights the importance of CD4+ Treg cells in post-stroke immune modulation and the impact of gender on the effect of these cells on stroke outcome." (PMID 40948641, 2025). "In contrast, the relationship between CD4+ Treg cell counts and stroke prognosis in female patients is more complex." (PMID 40948641, 2025). "The percentage of CD25-expressing CD4+ T cells increased following stroke compared to the age-matched control cohort at one month." (PMID 41373643, 2025). "Post-stroke CD4+ and CD8+ T cell activation (CD25) persisted for 1 month and declined only after 3 months." (PMID 41373643, 2025). "Nevertheless, our knowledge of the course of T cell activation in patients post stroke is still very limited: Data are available mainly on CD4+ T cells, few activation markers (HLA-DR, CD25, CTLA-4), and for a limited time span of 14 days." (PMID 41373643, 2025). "Among the T lymphocytes, helper T cells (CD4+ T cells) serve as biomarkers for predicting stroke outcomes." (PMID 39958615, 2025). "One of the SAI risk factors, next to older age, severe clinical status on admission, and large size of infarct lesions, is a decreased number of CD4+ T cells in the initial phase of stroke." (PMID 40342517, 2025). "The abundance of naïve T and NK cells increased in stroke patients, whereas that of CD4 + T cells and Mac decreased." (PMID 40303468, 2025). "Our data confirm the essential role of CD4+ Treg cells in controlling immunological response post-stroke." (PMID 40948641, 2025). "In other words, a higher CD4+/CD8+ ratio related to better clinical conditions for our patients at the beginning of the stroke." (PMID 40342517, 2025). "CD4+ Treg cell counts were measured by flow cytometry within 24 h of admission, and stroke prognosis was assessed at 3 months using the mRS." (PMID 40948641, 2025).
Stroke (continued). "We found that the higher the percentage of CD4+ T cells in the acute and subacute phases of stroke, the better the clinical status, while the higher the percentage of CD8+ T cells, the worse the clinical status." (PMID 40342517, 2025). "The amount of PD-L1+ in CD4+ T cells was highest in the “stroke t3” group and significantly higher than in the “stroke t1” group." (PMID 41373643, 2025). "The primary indicators of stroke-induced immunodepression (SIIS) include lymphopenia predominantly affecting CD4+ T cells, an increased neutrophil-to-lymphocyte ratio, and decreased expression of antigen-presenting molecules such as monocyte HLA-DR." (PMID 39633897, 2024). "This study aimed to explore the correlation of serum ATG5 with CD4+ T cells and cognition impairment in stroke patients." (PMID 38511768, 2024). "We thus isolated CD4+ T lymphocytes from peripheral mononuclear cells of healthy donors and stroke patients." (PMID 39372701, 2024). "This study also implemented flow cytometry to uncover the inversed association between stroke severity and CD69+CD4+ T cell phenotype." (PMID 39633897, 2024). "High percentages of CD4+CD28- T cells have been associated with instable angina and the increased risk of relapse of an acute coronary event or stroke." (PMID 39456708, 2024). "GPR55 inactivation noticeably attenuated the after-stroke decrease in spleen size and decreased CD4+T-cell spleen egress in tMCAO mice." (PMID 38334672, 2024). "In the first 24 hours after stroke, CD4+ Th1 and Th17 cells, as well as γδT and CD8+ cells are the predominant pro-inflammatory T cells, which secrete cytokines such as IL-17, TNF-α, infiltrate the infarcted area." (PMID 39676865, 2024). "Remarkably, however, platelet-derived soluble CD84 acts on CD4 + T cell CD84 leading to enhanced CD4 + T cell motility in vitro and aggravated infarct growth following experimental stroke." (PMID 39334369, 2024). "CD4+T cells [CD45hiCD11b−CD3+CD4+] recently have been shown to migrate into the ischemic brain 1–3 days post-stroke in the tMCAO model in mice." (PMID 38334672, 2024). "Our findings further support the inverse association between CD45RA on naive CD4+ cells and CD8 on CM CD8b with stroke occurrence." (PMID 38894965, 2024). "CD4+ T cells are slightly increased in stroke patients by scRNA-seq, while CD8+ T cells are identical in control and stroke patients." (PMID 39633897, 2024). "Stroke resulted in an almost 3-fold decrease in CFSE-positive CD4+CD3+T cells, whereas treatment with ML-193, a GRP55 antagonist, attenuated T-cell egress from the spleen by 62% ± 7%." (PMID 38334672, 2024). "CD4+ cells mainly exacerbate the progression of stroke by secreting cytokines that promote inflammatory responses." (PMID 37905592, 2023). "CD4 T cells play an important role in neurodegenerative diseases, such as Parkinson's disease (PD), AD, stroke, and Lewy body dementia." (PMID 37434203, 2023). "T regulatory cells and Th2 CD4+ T cells produce IL-10, the inflammatory signal after stroke; however, there are gender variations in the production of these cells." (PMID 36793730, 2023). "Weitbrecht and others reported that CD4+ T cells promote delayed B cell responses in the ischemic brain after stroke." (PMID 36650518, 2023). "Our findings confirm previously observed immunological changes in the immediate aftermath of a stroke, such as increased granulocyte counts, reduced numbers of CD4+-T-lymphocytes, and elevated levels of acute phase proteins." (PMID 37587512, 2023). "T cells rapidly sense injury and move to the hemorrhagic brain, where they accumulate in the regions surrounding the hematoma; T lymphocytes, primarily CD4+ cells, arrive at the perihematomal regions as early as 12 h following stroke." (PMID 35805099, 2022). "Studies have shown that the levels of CD4+, CD8+ T cells, and CD4+/CD8+ in the peripheral blood of patients with stroke are closely related to the severity and prognosis of AIS." (PMID 35656537, 2022).